TNF (tumor necrosis factor)
Diseases named in the same sentence as TNF in open-access papers (continued):
Sharing a sentence is not in itself a finding about the gene and the disease.
Insulin resistance (continued). "Pro-inflammatory cytokines, such as interleukin-6 (IL-6), tumor necrosis factor-alpha (TNF-α), and interleukin-1β (IL-1β), disrupt insulin signaling, impair β-cell function, and exacerbate insulin resistance." (PMID 41578487, 2026). "Pro-inflammatory cytokines such as TNF-α, IL-1β, and MCP-1 are key mediators of adipose tissue remodeling, promoting lipogenesis, hypertrophy, and insulin resistance." (PMID 41596279, 2026). "Hyperglycemia promotes elevated local levels of IL-1β, TNF-α, and MMP-9, which not only exacerbate periodontal tissue destruction but also contribute to systemic insulin resistance and β-cell apoptosis." (PMID 40283677, 2025). "There was a significant decrease in serum concentrations of insulin and the homeostasis model assessment of insulin resistance (HOMA-IR), triglycerides, TNF-α, and TBARS with ascending quartiles of serum Se." (PMID 40564877, 2025). "TNF attenuates the insulin-stimulated tyrosine phosphorylation of IRS1 in adipose tissue and muscle, resulting in the occurrence of insulin resistance." (PMID 39812542, 2025). "Tumor necrosis factor-alpha (TNF-α) inhibitors, such as etanercept, have been studied for their role in reducing insulin resistance and improving inflammatory profiles." (PMID 40218134, 2025). "Proinflammatory cytokines such as tumor necrosis factor-α (TNF-α), interleukin-6, and galectin-3, induce insulin resistance." (PMID 41374008, 2025). "Following activation, macrophages produce a number of pro-inflammatory mediators, including the cytokine tumor necrosis factor-alpha (TNF-α), that can induce insulin resistance in hepatocytes and trigger hepatocyte apoptosis." (PMID 40380177, 2025). "This transition results in increased secretion of cytokines such as TNF-α, IL-6, and monocyte chemoattractant protein-1 (MCP-1), which collectively drive systemic meta-inflammation and can contribute to the development of insulin resistance." (PMID 41301434, 2025). "In particular, cytokines such as IL-6, IL-1β, TNF-α, and CRP contribute to the development of insulin resistance." (PMID 40283443, 2025). "Research confirms higher C-reactive protein (CRP) levels in MetS patients are correlated with insulin resistance, blood pressure, poor HDL, triglycerides, and proinflammatory cytokine levels, including TNF and IL-6." (PMID 39817379, 2025). "Adipokine dysregulation, characterized by elevated leptin, resistin, and tumor necrosis factor-alpha (TNF-α) levels and reduced adiponectin, exacerbates hepatic insulin resistance and contributes to cellular stress." (PMID 40734888, 2025). "Considerably, hormonal imbalances, such as insulin resistance, altered adipokines, and inflammatory markers like highly sensitive-reactive protein (hs-CRP), IL-6, and TNF-α, are pivotal in fatty liver pathogenesis and cardiovascular risk." (PMID 39808219, 2025). "Vitamin E has preventive and protective effects on MASLD by improving hepatic steatosis (FLI, L/S ratio), insulin resistance (HOMA-IR), oxidative stress (MDA), inflammation (hs-CRP, TNF-α, IL-6, leptin, adiponectin), and hepatocyte apoptosis (CK18-M30)." (PMID 40668532, 2025). "M1 macrophages produce proinflammatory cytokines like TNF-α, IL-6, and monocyte chemoattractant protein (MCP-1), which reduce insulin signaling in different tissues, thus contributing to insulin resistance and the onset of T2D." (PMID 40362446, 2025). "Chronic inflammatory response exacerbates insulin resistance by triggering responses of C-reactive protein (CRP), tumor necrosis factor-alpha (TNF-α), and interleukin-6 (IL-6), resulting in T2DM and renal impairment and increasing uric acid levels." (PMID 40129592, 2025). "Since TNF-α is known to directly induce insulin resistance in adipocytes, TNF-α-treated 3T3-L1 adipocytes have been extensively utilized as an insulin resistance model." (PMID 39803918, 2025).
Insulin resistance (continued). "Pro-inflammatory cytokines IL-6, IL-1β, and TNF-α play a crucial role in MASLD-related inflammation and progression and hepatic insulin resistance." (PMID 40722894, 2025). "Overeating causes the accumulation of liver fats that contribute to the production of most adipokines, such as leptin, resistin, adiponectin, tumor necrosis factor-alpha (TNF-alpha), and IL-6, which are involved in inducing insulin resistance and inflammation." (PMID 41441034, 2025). "Among them, TNFα and MCP-1 are important mediators involved in catabolic responses and metabolic disturbances such as insulin resistance." (PMID 40332596, 2025). "This proinflammatory cascade, driven by cytokines such as IL-6, TNF-α, and MCP-1, promotes macrophage infiltration and activates the NF-κB/JNK pathway, ultimately contributing to systemic insulin resistance." (PMID 41471698, 2025). "Biomarkers such as CRP, IL-6, and TNF-α serve as indicators of inflammation, while HOMA-IR, fasting insulin, and HbA1c are essential for evaluating insulin resistance." (PMID 40002771, 2025). "The swimming treated group had a significant reduction on final weight, weight gain,LDL, insulin resistance, MDA and TNFα and significantly increased HDL as compared to control group." (PMID 39762333, 2025). "At the same time, COVID-19 can activate the immune system, leading to the production of a range of cytokines such as interleukin-6 (IL-6) and tumor necrosis factor-alpha (TNF-α), which induce insulin resistance and hyperglycemia." (PMID 40046873, 2025). "Overexpression of miR-16 increased IGFBP3 levels by decreasing TNF-α and SOCS3 signaling, inhibited insulin resistance, and protected retinal endothelial cells from HG-treated apoptosis." (PMID 40166052, 2025). "The chronic inflammation interferes with insulin signaling through cytokines, such as Tumor necrosis factor-α and Interleukin- 6(TNF-α and IL-6), and inhibits adipocyte differentiation, leading to insulin resistance and lipid accumulation." (PMID 41019065, 2025). "Subsequently, inflammatory cytokines like tumor necrosis factor alpha (TNFα), interleukin 6 (IL6), and interleukin 1 beta (IL1β) exacerbate insulin resistance and metabolic dysfunction." (PMID 40687133, 2025). "Studies on insulin resistance have shown that high GGT coincides with an increase in inflammatory interleukins and tumor necrosis factor‐alpha (TNF‐ α)." (PMID 39817495, 2025). "In skeletal muscle cells, these peptides modulate tumor necrosis factor (TNF)‐α‐induced inflammatory signals, highlighting their potential to address inflammation and insulin resistance." (PMID 40761488, 2025). "These microbial changes correlate with systemic inflammation, elevated IL-6, TNF-α, and CRP, as well as insulin resistance (HOMA-IR)." (PMID 40308637, 2025). "Its anti-inflammatory properties also contribute to its metabolic benefits by suppressing pro-inflammatory cytokines (IL-6, TNF-α) and inhibiting the NF-κB and TLR4 signaling pathways, which are often upregulated in dyslipidemia and insulin resistance." (PMID 40509408, 2025). "This process upregulates pro-inflammatory cytokines, such as tumor necrosis factor-alpha (TNF-α) and interleukin-6 (IL-6), contributing to endothelial dysfunction and insulin resistance." (PMID 41002774, 2025). "Nevertheless, adipose tissue, now recognized as an endocrine organ, secretes multiple adipokines (e.g., leptin, adiponectin, visfatin) and inflammatory mediators (TNF-α, IL-6, MCP-1) that foster insulin resistance and endothelial dysfunction." (PMID 40149704, 2025). "TNF-α and SOCS3 establish a positive feedback loop that amplifies their expression and intensifies insulin resistance through sustained inflammatory pathway activation in AT." (PMID 40630101, 2025). "Macrophages in the pancreas are main suppliers of IL-1β, IL-6, IL-12, TNF (tumor necrosis factor)-α, IFN (interferon)-γ and nitric oxide (NO) which are largely responsible for the beta-cell dysfunction/death and the insulin resistance." (PMID 40259265, 2025).
Insulin resistance (continued). "Further, a strong positive correlation between insulin resistance index (HOMA-IR) and IL-6, TNF-α, and MDA of liver." (PMID 40229885, 2025). "As a myokine, TNF-a inhibits AMPK activity, thereby decreasing fatty acid oxidation and ACC phosphorylation, and eventually resulting in insulin resistance in skeletal muscle." (PMID 39812542, 2025). "Furthermore, elevated TyG levels are frequently linked to chronic inflammatory responses, characterized by increased concentrations of proinflammatory cytokines such as TNF-α and IL-6, which may further impede insulin receptor signaling and exacerbate insulin resistance." (PMID 40626240, 2025). "TNF-α was the first cytokine targeted for metabolic indications, based on strong preclinical evidence linking TNF-α to adipose tissue inflammation and insulin resistance." (PMID 41463063, 2025). "TNF-α directly impairs insulin signalling by increasing serine phosphorylation of insulin receptor substrates (IRS), promoting insulin resistance." (PMID 40700071, 2025). "In in vitro studies and in animal models, TNF-alpha actives c-JUN N-terminal kinase (JNK) 1 and IκB kinase (IKK), which in turn inhibit insulin receptor activation, which can lead to insulin resistance." (PMID 40218888, 2025). "Insulin resistance often triggers a state of low-grade chronic inflammation, activating immune cells and releasing pro-inflammatory cytokines like CRP, IL-6, and TNF-α." (PMID 40002771, 2025). "VAT expansion increases proinflammatory cytokines (e.g., interleukin-6 [IL-6], tumor necrosis factor-alpha [TNF-α]), driving insulin resistance, and reduces adiponectin, exacerbating metabolic dysregulation." (PMID 41163040, 2025). "Pro-inflammatory adipokines, such as leptin, resistin, visfatin, tumor necrosis factor-alpha (TNF-α), IL-1beta, IL-6, and IL-8, among others, increase insulin resistance and exert atherogenic effects." (PMID 39941348, 2025). "Adipose tissue—particularly visceral fat—secretes inflammatorycytokines (e.g., IL-6, TNF-α), activating the TLR4/NF-κBpathway, which induces insulin resistance, endothelial dysfunction, andatherosclerotic plaque formation." (PMID 41356294, 2025). "Periodontitis has been shown to induce systemic inflammation via the release of inflammatory mediators, such as interleukin-6 (IL-6) and tumor necrosis factor-alpha (TNF-α), which exacerbate insulin resistance and glycemic dysregulation." (PMID 40458179, 2025). "IL-6 and TNF-α are known to influence lipid metabolism and GLUT4 expression, contributing to the development of insulin resistance." (PMID 40142333, 2025). "Primary outcomes included insulin resistance (HOMA-IR), insulin sensitivity (Matsuda index), mtDNA DAMPs (ND1, ND6), pro/anti-inflammatory cytokines (IFN-γ, IL-10, IL-6, IL-8, TNF-α), CRP, and cortisol." (PMID 41156500, 2025). "NFκB activation further induces the release of pro-inflammatory cytokines such as IL-6, TNFα, ICAM-1, and VCAM-1, which ultimately exacerbates insulin resistance in diabetic patients." (PMID 40369521, 2025). "Adipokines, including interleukin-6 (IL-6), tumor necrosis factor-alpha (TNF-α), and free fatty acids, can lead to insulin resistance, oxidative stress, and mitochondrial dysfunction that ultimately lead to renal damage." (PMID 40936744, 2025). "TNF-α, which is present in higher quantities in ERDS patients, blocks phosphorylation of insulin receptors, contributing to insulin resistance in these patients." (PMID 40725745, 2025). "Statins have also been associated with heightened systemic inflammation, characterized by elevated levels of pro-inflammatory markers such as interleukin-6 (IL-6) and tumor necrosis factor-alpha (TNF-α), which exacerbate insulin resistance." (PMID 39981479, 2025). "In adipocytes, insulin resistance and inflammation lead to synthesis and release of NEFA and pro-inflammatory cytokines, such as interleukin-6 (IL-6) or tumor necrosis factor (TNF)." (PMID 41012462, 2025).
Insulin resistance (continued). "Mechanistically, insulin resistance in T2DM promotes both adiposity and muscle catabolism, while chronic low-grade inflammation (e.g., elevated TNF-α and IL-6) accelerates muscle degradation." (PMID 40955268, 2025). "Visceral adipose tissue (VAT) is metabolically active, secreting pro-inflammatory cytokines such as interleukin-6 (IL-6) and tumor necrosis factor-alpha (TNF-α), thereby contributing to systemic inflammation and insulin resistance." (PMID 40521354, 2025). "Tumor necrosis factor-alpha (TNF-α) impairs glucose uptake in adipose and muscle tissues through MAPK and IKK pathway activation, directly contributing to insulin resistance." (PMID 41305652, 2025). "TNF can activate STAT3, HIF-1a, Th17, and IL-6, while IL-1 can induce insulin resistance, HIF-1 production, and JAK-STAT signals." (PMID 39891057, 2025). "First, the elevated levels of TNF‐α and IL‐6 in the presence of CRC can lead to insulin resistance, making it harder for muscle cells to utilize glucose effectively." (PMID 38924332, 2024). "At the core of this cluster lies tumor necrosis factor alpha (TNF-α), which activates JNK and IKKβ signaling, sustains adipose inflammation, and promotes insulin resistance." (PMID 38672413, 2024). "TNF-α impairs insulin action by activating JNK and IKKβ pathways, disrupting insulin signaling, while IL-1β and IL-6 exacerbate insulin resistance by inhibiting receptor functions and glucose uptake." (PMID 39458518, 2024). "One of the signaling pathways involved in the inflammatory mechanisms is the activation of JNK1 by TNF-α, which results in serine phosphorylation of insulin receptor substrate 1 (IRS1) and impairs insulin signaling and subsequent insulin resistance." (PMID 39065815, 2024). "It was found that some key inflammatory mediators of COPD, particularly IL‐6, TNF‐α, and TGF‐β, also play hub roles in insulin resistance and diabetes." (PMID 39187923, 2024). "These targets mainly focus on the PI3K-Akt signaling pathway related to T2DM, AGE-RAGE signaling pathway in diabetic complications, tumor necrosis factor (TNF) signaling pathway, and insulin resistance." (PMID 38470866, 2024). "TLRs stimulate NFKB and JNK signaling, which also lead to upregulation of the expression of inflammatory cytokines including TNFα and IL6, and further induce insulin resistance in adipocytes and macrophages." (PMID 39264906, 2024). "While various potential markers were considered, the analysis highlighted TNF-α for inflammation and HOMA C-peptide for insulin resistance as particularly significant." (PMID 38672121, 2024). "At the concentration of 10 μM, the VC067 complex reversed the decrease in [14C]-deoxy-D-glucose transport in hepatocytes in which insulin resistance was induced by oleic acid, and the VC068 complex reversed the decrease in transport induced by TNF (p ≤ 0.05)." (PMID 38399444, 2024). "Further, significant decreases in IL-1β, TNF-α and ALT activities were also found in mice of the RQP group, which were inflammatory factors and play vital role in the development of insulin resistance in T2D cases." (PMID 38476942, 2024). "In the milieu of T2DM, elevated chronic plasma levels of TNF-α, a consequence of ADAM17's shedding activity, promote insulin resistance, thereby decreasing the activation of the PI3K/AKT pathway." (PMID 38963109, 2024). "Chronic oxidative stress also promotes the release of pro-inflammatory cytokines like tumor necrosis factor-alpha (TNF-α), which further exacerbates insulin resistance." (PMID 39857603, 2024). "These inflammatory mediators, such as (but not limited to) TNFα, IL-6, and MCP-1, which are produced by myocytes or obese skeletal muscle, have been shown to contribute to impaired glucose uptake and insulin resistance." (PMID 38398822, 2024). "IL‐6 and TNF exert inhibitory effects on the expression of glucose transporter type 4 (GLUT‐4), potentially promoting insulin resistance when their levels rise." (PMID 38874882, 2024).
Insulin resistance (continued). "Fasting blood sugar (FBS), insulin resistance (IR), total antioxidant capacity (TAC), malondialdehyde (MDA), C-reactive protein (CRP), tumor necrosis factor-alpha (TNF-α), and AMH were measured before and after the study." (PMID 38778429, 2024). "Given that insulin resistance is a key factor in the development of diabetes, it is plausible to consider whether oxidative stress, along with the elevated release of IL-1, IL-6, and TNF in AS, could lead to insulin resistance, thereby playing a role in the development of diabetes." (PMID 39649224, 2024). "RJ also significantly reduced the TNF and IL-6 levels in the adipose tissue of the HFD-fed rats, potentially attributable to its anti-inflammatory effects or its role in ameliorating insulin resistance." (PMID 39339774, 2024). "The inflammatory pathways via TNFα, TLR4, NFκB, and NLRP3, improves insulin resistance and these pathways are the targets of metformin which will be mentioned in following sections." (PMID 38311861, 2024). "Inflammatory cytokines, such as Tumor Necrosis Factor (TNF) α and IL-6, disrupt the insulin signaling pathways, exacerbating hepatic insulin resistance and promoting steatosis, liver injury, and fibrosis." (PMID 38999756, 2024). "Before-and-after data suggest an improvement in totalcholesterol, LDL, triglycerides, insulin resistance, C3, GCF levels of TNF-α,chemerin, vaspin, omentin-1, visfatin, 8-OHdG, and periodontal pathogen countsafter therapy." (PMID 38597549, 2024). "Our findings demonstrated that both 12 weeks of AT and saffron supplementation alone significantly affected serum levels of glucose, insulin resistance, FIB, HCY, IL‐6, and TNFα in diabetic patients." (PMID 38874882, 2024). "In humans, ADAM17 expression and enzymatic activity were increased in T2DM skeletal muscle, as were the substrates TNF-α and IL6-R, which positively correlated with insulin resistance." (PMID 38963109, 2024). "In theory, TNF-α inhibition should benefit patients with psoriasis and NAFLD by decreasing insulin resistance, which is central to both conditions." (PMID 38473907, 2024). "Effects on fasting glucose and insulin, Homeostatic Model Assessment of Insulin Resistance (HOMA-IR), HbA1c, adiponectin, leptin, IL-6, TNF-α, and C-reactive protein (CRP) in exercise vs control groups were analyzed using random effects meta-analysis." (PMID 38253590, 2024). "Excessive Aβ inhibits the insulin binding ability of InsRs to some extent, and this further exacerbates insulin resistance by activating JNK/TNF-α pathways and inducing IRS-1 phosphorylation." (PMID 38818523, 2024). "Tumor necrosis factor-α (TNF-α) stimulates free fatty acid (FFA) secretion through adipocyte lipolysis, and increased plasma levels of FFA promote insulin resistance." (PMID 39086546, 2024). "Given the close link between dyslipidemia, chronic low-grade inflammation, and insulin resistance, a comparative analysis of serum biochemical parameters (HDL-C, LDL-C, TC, TG) and plasma inflammatory factors (IL-6, TNF-α) was conducted." (PMID 38708085, 2024). "Diabetics and overweight individuals, but also periodontitis patients, have been shown to have elevated serum TNF-α and IL-6 levels, which can induce CRP production, impair intracellular insulin signaling, and lead to insulin resistance for type II diabetes." (PMID 39767238, 2024). "Our results that galantamine treatment reduced inflammatory cytokines (TNF-α, IL-6, HMGB-1), improved insulin resistance and glycemic control in the db/db mice are consistent with those of the clinical trial of galantamine in patients with metabolic syndrome." (PMID 37731032, 2023). "EPA and DHA supplementation improved metabolic (insulin, Homeostatic Model Assessment of Insulin Resistance [HOMA-IR], triglyceride [TG]/ high-density lipoprotein [HDL] ratio, TG, and arachidonic acid [AA]/EPA ratio) and tumor necrosis factor-alpha (TNF-α)." (PMID 37215211, 2023).